IL6 (interleukin 6)
Diseases named in the same sentence as IL6 in open-access papers (continued):
Sharing a sentence is not in itself a finding about the gene and the disease.
cerebral infarction (continued). "We found that measurement of PC-Acro together with IL-6 and CRP makes it possible to identify SBI with high sensitivity and specificity and can decrease the number of people with cerebral infarction as mentioned in the introduction." (PMID 36830667, 2023). "Increases the levels of A subunit and B subunit in GABA and IL-1β, IL-6, TNF-α to reduce neurological deficit and cerebral infarct area." (PMID 35548468, 2022). "Cerebral levels of IL-6, IL-10, TNF-α, NF-κB p65, and ICAM-1, besides cerebral infarct volume, were significantly elevated in control and vehicle related to sham groups, while total antioxidant capacity was markedly reduced." (PMID 36567842, 2022). "Results showed that casticin reduced the volume of the cerebral infarction, mNSS scores, swimming distance, time to find the submerged platform, and serum concentrations of TNF‐α, TGF‐β, IL‐6 in MCAO rats." (PMID 33704926, 2021). "The miR-137 downregulated Src reducing cerebral infarction volume by inhibiting release of inflammatory markers such as TNF-α, IL-1, IL-6 and IL-17, p-ERK 1/2, p-38, and p-JNK and also improving cognitive functions in MCAO rats." (PMID 34684090, 2021). "Geniposide has been shown to significantly reduce the area of cerebral infarction and alleviate neuronal damage and necrosis mainly by inhibiting inflammatory signals, including NLRP3, TNF-α, IL-6, and IL-1β." (PMID 34454545, 2021). "The systematic review and meta-analysis will assess the effect of acupuncture on the expression of inflammatory factors TNF-α, IL-6, IL-1 and CRP in cerebral infarction with up-to-date clinical evidence." (PMID 31192907, 2019). "The combined extract also decreases the brain infarction, MDA, IL-6, and NF-κB levels but increases the activities of antioxidant enzymes, the expression of eNOS in the frontal cortex." (PMID 31827714, 2019). "Here, we demonstrated that EGB markedly reduced pro-inflammatory cytokines/chemokines levels, including those of IL-6, IL-α and CXCL10, in tissues surrounding the cerebral infarction." (PMID 29867513, 2018). "The present study showed that Sino significantly decreased the mRNA levels of pro-inflammatory cytokines, including IL-1β, IL-6, IL-18, and TNF-α, in the tissues surrounding the cerebral infarction." (PMID 27724964, 2016). "Studies have shown that Genipin could significantly reduce the area of cerebral infarction and attenuate neuronal damage and necrosis by inhibiting inflammatory factors such as NLRP3, TNF-α, IL-6, and IL-1β." (PMID 39679371, 2024). "There was no significant positive correlation between IL-6 and cerebral infarction volume (R < 0.3), but there was statistical significance (r = 0.177, P = 0.036)." (PMID 36643631, 2023). "A previous study demonstrated that cerebral infarction triggers the TLR signaling activation-induced inflammatory responses, further leading to the expression of NF-κB-mediated inflammatory cytokines, such as IL-1, IL-6, IL-8, and TNF-α." (PMID 35966335, 2022). "As pointed out, our data suggest that high CSF IL-6 levels will not identify patients who benefit from DCI treatment but rather those who will ultimately develop cerebral infarcts." (PMID 33420113, 2021). "In the acute phase of cerebral I/R injury, SP600125 treatment reduced cerebral infarction by inhibiting the expression of inflammatory mediators including TNF-α, IL-1β, IL-6, and matrix metalloproteinase-9 and downregulating the mitochondria-mediated apoptotic pathway in the ischemic area." (PMID 34419138, 2021). "Previous studies have reported that TLR4-mediated signaling causes JNK, p38 MAPK, and NF-κB activation, which induces the production of pro-inflammatory factors, including iNOS, COX-2, TNF-α, and IL-6, in the ischemic area, further exaggerating BBB disruption and cerebral infarction." (PMID 34419138, 2021).
cerebral infarction (continued). "Furthermore, the effects of YZR extract treatments on cerebral infarction are partially due to the suppression of JNK/NF-κB-mediated iNOS, COX-2, TNF-α, and IL-6 expression in the penumbral cortex at 1 day after reperfusion." (PMID 34419138, 2021). "The HFD group presented a significant increase in brain infarct volume (38.7 (IQR 30–46.7%) vs. 28.45 (IQR 21–30%); p = 0.016) and HT (HFD: 2 (IQR 1–5) vs. ND: 0 (IQR 0–1); p = 0.012) and higher levels of IL-6 and MCP-1 in infarcted hemisphere compared to the ND group." (PMID 33925459, 2021). "Additionally, outcomes included neurological deficit score, brain edema, cerebral infarction area, neuronal apoptosis, serum levels of inflammatory factors (TNF-α, IL-6, and IL-1β), and the antioxidant level of body (SOD, MDA, and GSH-Px)." (PMID 30581490, 2018). "Hydroxysafflor yellow A, a major active component of C. tinctorius L. (Hong Hua), reduces cerebral infarction by suppressing cytosolic NF-κBp65 translocation to the nucleus and subsequently downregulates NF-κB-mediated TNF-α, IL-1β, and IL-6 expression in the ischemic area 24 h after permanent MCAo." (PMID 27703487, 2016). "The TRPV4 antagonist GSK2193874 or EA‐mediated TRPV4 suppression reduces cerebral infarction and neurological dysfunction in the MCAO/R model by suppressing the activation and proinflammatory polarization of microglia and the mRNA levels of Tnf‐α, Il‐6, and ccl2." (PMID 41399206, 2025). "Furthermore, small brain infarction without obvious symptoms was identified with approximately 84% sensitivity and specificity by measuring PC-Acro together with interleuklin-6 (IL-6) and C-reactive protein (CRP) in plasma in clinical studies." (PMID 36830667, 2023). "The higher levels of proinflammatory tumor necrosis factor (TNF-α), interleukin-6 (IL-6), and interferon-gamma (IFN-γ) in the plasma of focal cerebral ischemia monkeys suggest both intestinal microecological dysregulation and chronic systemic inflammation following cerebral infarction." (PMID 36267243, 2022).
dry eye (99 papers, 2009 to 2026). "In conclusion, our study demonstrates that aqueous‐deficient dry eye significantly compromises corneal epithelial and nerve regeneration by sustaining inflammation mediated through the NF‐κB/IL‐6 signaling pathway." (PMID 41208970, 2025). "Although IL6 has been well known as an important cytokine on disease progression and severity associated with immune mechanisms, its role in dry eye was still vague except for increased expression on the ocular surface." (PMID 27555966, 2016). "It has been reported that tear IL-6 levels are significantly increased in dry eye patients and the expression of IL-6 was upregulated in conjunctival tissues in Sjögren syndrome, a major cause of dry eye." (PMID 27047687, 2016). "This not only suggests a genetic predisposition of dry eye for certain populations, but also supports the use of IL-6 as a marker of dry eye in susceptible people." (PMID 26605353, 2014). "Desiccating stress in the murine dry eye model, similar to human dry eye, also causes ocular surface inflammation characterized by increasing IL-6 and IL-17A expression." (PMID 23956763, 2013). "Although a recent study with patients with dry eyes in aqueous-deficient patients suggested that elevated IL-6 levels in tear fluid had to be considered as a Th17 promoting response, the levels of IL-17 were not assessed." (PMID 22509110, 2012). "These cytokines were associated with different clinical features: IL-6 with complaints of dry eyes, OSDI scores and corneal staining whereas IFN-γ showed an association with decreased TBUT and low Schirmer test score." (PMID 22509110, 2012). "Furthermore, LPA also showed that higher levels of IL-6 and IL-8 in subgroup 1 patients was associated with a greater composite dry eye severity score of signs." (PMID 38177232, 2024). "In this study, tear fluid IL-6 and IL-8 concentrations correlated with various clinical signs of dry eye in T2D with DED and could potentially be diagnostic biomarkers of T2D-related DED." (PMID 37367891, 2023). "IL-6, along with other pro-inflammatory cytokines, plays a major role in the pathogenesis of several inflammatory disease such as dry eye, graft-versus-host disease, and thyroid-associated ophthalmopathy through NF-κB and mitogen-activated protein kinase (MAPK) pathways." (PMID 27517861, 2016). "Further, it is reported that production of the inflammatory cytokines, interleukin (IL)-1, IL-6, and IL-8, in the tear membrane is increased in patients with dry eyes." (PMID 39596346, 2024). "Clinical cases of dry eye have also shown increased expression of the IL-23/Th17 axis, leading to higher levels of IL-6, IL-23R, TGF-β2, and the transcription factor RoRγt." (PMID 38898418, 2024). "Dry eye is accompanied by inflammation with increased levels of inflammatory and T cell-related mediators such as IL-1β, IL-6, TNF-α, IL-17, and IFN-γ, noted in the conjunctiva and tear fluid of dry eye patients." (PMID 36830827, 2023). "The mRNA expression of miR-146a, TNF-α, IL-1β, IL-6 and IL-8 in the corneas of dry eye model mice was measured by real-time quantitative PCR (RT-qPCR)." (PMID 37433841, 2023). "Inflammation caused by postoperative dry eyes can increase the levels of inflammatory cytokines in tears, such as IL − 1a and IL-1b, TNF-a, IL-6, and IL-8, several of which play key roles in epithelial hyperproliferation and keratinization." (PMID 38259844, 2023). "Immunofluorescent staining results also indicated an increase in inflammatory cytokines such as IL-1β, IL-6, and TNFα in the dry eye group, while the dry eye + LED group exhibited an overall significant decrease." (PMID 38139321, 2023). "It has been shown that dry eye-related inflammatory mediators (TNFα, IL-1β, IL6/IL17, and prostaglandin E2) upregulate MUC5AC mRNA expression." (PMID 36209216, 2022).
dry eye (continued). "Previous studies have shown that innate immune system-mediated inflammation occurs in dry eye, leading to the expression of proinflammatory cytokines, including IL-1β and IL-6, on the ocular surface." (PMID 36013601, 2022). "Kaempferol can promote tear production and corneal repair by inhibiting proinflammatory factors such as IL-1B, IL-6, IL-8, and TNFα and has significant therapeutic effects in rabbit dry eye models." (PMID 36590763, 2022). "It should be considered that the regulation of osmolarity has a great impact on the dry eye inflammatory cycle, leading to significant reduction of inflammatory markers in tears (especially IL-17A and IL-6), as demonstrated in previous reports." (PMID 35361273, 2022). "The phosphorylation of NF-KB was reduced along with a decrease in TNF-α, IL-1β, and IL-6 in BAC-induced dry eye mice following treatment with KIOM-2015E." (PMID 36499298, 2022). "Once the NF-κB signaling pathway is inhibited, the expression of IL-1β, TNF-α, and IL-6 on the ocular surface of dry eye, as well as the activation of immune cells, can be down-regulated." (PMID 35812407, 2022). "Tear-derived inflammatory biomarkers include tumor necrosis factor alpha (TNF-α), interleukin 6 (IL-6), IL-8, and IL-17, which are all elevated in dry eyes." (PMID 35886858, 2022). "In terms of the dry eye–related expression of inflammatory factors, the levels of IL-1β and IL-6 were assessed using qRT-PCR." (PMID 35185587, 2022). "qRT–PCR revealed increased inflammatory IL-1β, IL-6, IL-8 expression at 24 h following the induction of dry-eye and 24 h treatment with 100 μL sodium hyaluronate 0.15% (SH) in comparison with the control corneal tissue (p < 0.001; Student’s t-test)." (PMID 34959420, 2021). "The significantly affected dry eye-related markers were correlated with significant changes in IL-6, IL-8, IFN-γ, and TNF-α levels." (PMID 34957146, 2021). "In this study, we selected several inflammatory cytokines associated with dry eye, including IL-17A, IL-10, IL-12p70, INF-γ, IL-6, and TNF-α." (PMID 34659636, 2021). "TNF-α and IL-6 are important factors of goblet cell apoptosis and dry eye symptoms in patients with concomitant exotropia." (PMID 34659636, 2021). "Our transcription analysis of the gene signature for epithelial dryness in corneal tissue confirmed previous clinical findings showing increased production of proinflammatory cytokine expression levels (IL-6, 8, 1β) during stressed dry eye conditions." (PMID 34959420, 2021). "Increasing trends of IL-6 and IL-8 were found at 1 (p = 0.016, p = 0.031) and 3 months (p = 0.016, p = 0.047) postoperatively in subjects with dry eye." (PMID 34957146, 2021). "qPCR analysis revealed that the mRNA levels of TNF-α, IL-1β, and IL-6 in dry eyes were significantly up-regulated by 3.0, 2.6, and 3.3-fold, respectively, compared to the NS mice." (PMID 34445121, 2021). "In cornea and conjunctiva of normal or dry eye model mice, the mRNA expression levels of IL-1β, IL-6, IL-8, TNF-α, IFN-γ, and MMP-9 were investigated by real-time PCR in the presence or absence of isorhamnetin." (PMID 33921231, 2021). "The most widely studied pro-inflammatory cytokine accompanying dry eye is Interleukin (IL)-1 alongside IL-6, IL-8, IL-1β and TNFα which is also known to play a significant role in DES-related inflammation." (PMID 32629860, 2020). "The instillation of 0.2% BAC for 5 consecutive days, twice daily, deteriorated some signs of dry eye such as tear breakup time, fluorescein corneal staining, conjunctival hyperemia, density of goblet cells, height of mucin cloud, and levels of IL-6 mRNA." (PMID 32566267, 2020). "A study in patients with thyroid orbitopathy (TO) related dry eye, demonstrated increased levels of conjunctival cytokines IL-1α, IL-1β and IL-6 in IC samples using immunofluorescence." (PMID 30673862, 2019).
dry eye (continued). "Dry eye patients were found with higher levels of proinflammatory cytokines such as IL1α along with IL-1β, IL-6, IL-8, and tumor necrosis factor (TNF-α) in the tear film compared to normal controls." (PMID 30519584, 2018). "Patients with more severe dry eye have increased levels of IL-6 and IL-8/CXCL8 in their tears and similar increases are seen in the conjunctival epithelium in experimental dry eye models." (PMID 30002412, 2018). "In a hyperosmotic environment, pro-inflammatory cytokines such as interleukin-6 (IL-6), interleukin-8 (IL-8), and IL-1β are detected in corneal cell lines or dry eye patients." (PMID 28261099, 2017). "The promising results of lutein on the inhibition of hyperosmoticity-induced elevation of IL-6 expression obtained from the present study support further investigation of the use of lutein in the treatment of dry eye." (PMID 27047687, 2016). "There were significant correlations between IL-6 and parameters of dry eye, and between MGD parameters and ocular symptom scores." (PMID 27695117, 2016). "In the dry eye group, the initial concentrations of IL-1β, IL-6, IL-8, MCP-1, TNF-α and IFN-γ were 57.78 ± 5.25, 214.73 ± 18.17, 500.30 ± 38.69, 1518.42 ± 143.29, 385.11 ± 21.95, and 96.55 ± 8.19 pg/ml, respectively." (PMID 27695117, 2016). "IL6 has been known as a representative cytokine with increased expression in tears and the conjunctival epithelium of eyes with dry eye syndrome." (PMID 27555966, 2016). "In previous studies increased levels of ribonucleic acid transcripts encoding IL-1, IL-6, TGF-β1, and TNF-α and were detected in the conjunctiva of patients with keratoconjunctivitis sicca." (PMID 27695117, 2016). "In another study, higher levels of IL-17A, TGF-β1, TGF-β2, IL-6, IL-23, and IL-1 mRNA transcripts were observed in the corneal epithelium and conjunctiva of dry eye mice." (PMID 25590134, 2015). "In the dry eye model of rats, the IL-6 and TNFα mRNA level in the cornea measured by real-time RT-PCR increased." (PMID 26818460, 2015). "Expression of interleukin 6 (IL-6) and TNFα is upregulated by local tissue dryness in conjunctiva of dry eye patients and experimental dry eye model." (PMID 26818460, 2015). "Tear IL-6 levels correlated with complaints of dry eyes (r=0.39, p=0.02), tear production (r=-0.59, p<0.0001), fluorescent staining of the cornea (r=0.42, p=0.01), and with the OSDI score (r=0.40, p=0.005)." (PMID 22509110, 2012). "After desiccation, the corneas of the dry eye model rat were collected to isolate total RNA and the levels of expression of IL-6 and TNF-α were determined by TaqMan real-time PCR." (PMID 21976951, 2011). "In the dry eye model rats, the IL-6 mRNA level in the cornea significantly increased, whereas TNF-α mRNA level slightly increased." (PMID 21976951, 2011). "In the multifactorial dry eye syndrome, there appears to be increased production of proinflammatory cytokines such as interleukin-1 (IL-1), interleukin-6 (IL-6), interleukin-8 (IL-8), tumor necrosis factor-alpha (TNF-α), and proteolytic enzymes." (PMID 19753313, 2009). "As QMR can decrease IL-6 levels, it may eliminate one of the factors leading to the vicious cycle of dry eye and MGD." (PMID 40579435, 2025). "Here we found not only do dry eye‐related inflammatory factors such as NFκB, IL‐6 and IL‐8 show significant activation, but the proliferation and stemness of limbal stem cells, along with the visualization of functional mucin protein, can also be observed in this model." (PMID 38961590, 2024). "TNF-α, IL-1β, and IL-6 are major markers of ocular surface inflammation in dry eye." (PMID 38399289, 2024). "Secondly, azithromycin suppresses conjunctival inflammation, which may block the activation of nuclear factor-kappa B (NF-κB), leading to decreased inflammatory cytokine levels such as interleukin-6 and -8 to improve dry eye symptoms." (PMID 35887783, 2022).